TSLP (thymic stromal lymphopoietin)
Diseases named in the same sentence as TSLP in open-access papers (continued):
Sharing a sentence is not in itself a finding about the gene and the disease.
eczema (continued). "The induction of TSLP protein expression occurred only in patients with a positive APT result, suggesting a role for TSLP in HDM induction of AD-related eczema." (PMID 28451053, 2017). "In mice, TSLP expression can be induced by application of the 1,25-dihydroxyvitamin D3 (VD3) analogue calcipotriol and results in the development of eczema-like lesions." (PMID 25866638, 2015). "We describe the development of the first putative, non-proteinic TSLP inhibitors which can also be applied locally onto the skin, thus significantly expand the treatment options for eczema patients." (PMID 38877290, 2024). "Although the VD3A-induced AD mouse model is of use in studying an AD-like phenotype in mice, our results indicate that the VD3 dependent mechanisms involved in the induction of TSLP and subsequent eczema in mice do not translate directly to human AD." (PMID 25866638, 2015). "Compared to that in HC, TSLP was significantly expressed semiquantitatively in the stratum basale of the epidermis with PsV (p = 0.002) and sarcoidosis (p =0.025) specimens and not significantly expressed in LP (p = 0.102), DLE (p = 0.360), eczema (p = 0.253), BP (p = 0.145), and MF (p = 0.436)." (PMID 36046760, 2022). "Similarly, TSLP was significantly expressed in the stratum spinosum of the epidermis in LP (p = 0.002), BP (p = 0.031), PsV (p = 0.002), eczema (p = 0.041), and MF (p = 0.046) specimens and not significantly expressed in DLE (p = 0.217) and sarcoidosis (p = 0.309)." (PMID 36046760, 2022). "The differences of TSLP expression between the stratum basale and the stratum spinosum in other dermatoses were not significant (DLE p = 0.584, eczema p = 0.153, BP p = 0.146, PsV p = 0.777, and MF p = 0.173)." (PMID 36046760, 2022).
cervical carcinoma (22 papers, 2018 to 2025). A carcinoma arising from either the exocervical squamous epithelium or the endocervical glandular epithelium. "In addition, TSLP plays a role in the mechanisms underlying the TME of cervical cancer, gastric, and ovarian cancer." (PMID 35936012, 2022). "TSLP protein in cervical cancer cells is induced by hypoxia; high TSLP expression is an important regulator of cervical cancer progression by recruiting and licencing tumour-associated eosinophils, which promote the growth of cervical cancer cells." (PMID 33652749, 2021). "This group extended the previous findings showing that TSLP released from cervical cancer cells can activate eosinophils to produce proinflammatory cytokines." (PMID 40873585, 2025). "The authors concluded that TSLP released from human cervical cancer can promote tumor angiogenesis through the activation of TSLPR on endothelial cells." (PMID 40873585, 2025). "TSLP examined by immunohistochemistry was overexpressed in human cervical cancer compared to cervicitis." (PMID 40873585, 2025). "Mechanistically, TSLP derived from cervical cancer cells up-regulated the levels of anti-inflammatory cytokines (IL-10, IL-4, IL-5 and IL-13) in eosinophils, which in turn promoted the proliferation and restricted the apoptosis of tumor cells." (PMID 40050933, 2025). "TSLP induced proliferation of human umbilical vein endothelial cells (HUVEC) expressing TSLPR and cervical carcinoma cell-derived TSLP promoted HUVEC proliferation." (PMID 40873585, 2025). "Many reports have noted that TSLP-dependent inflammatory Th2-type response and pro-tumorigenic functions play roles in pancreatic, breast, and cervical cancers." (PMID 38025525, 2023). "A model of cervix carcinoma also revealed that eosinophils, activated by tumor-generated thymic stromal lymphopoietin (TSLP), triggered tumor growth." (PMID 35563461, 2022). "TSLP also promotes tumour proliferation and invasion of cervical cancer cells through down-regulation of miR-132 expression." (PMID 33652749, 2021). "TSLP pathway has been found to relate to the progression of several human cancers, including breast, pancreatic, gastric and cervical cancer, as well as B cell lymphoma and myeloma, via generating type 2–biased inflammation in the tumor microenvironment." (PMID 32850805, 2020). "Previous studies show that tumour-derived TSLP interacts with endothelial cells to promote angiogenesis in cervical cancer, resulting in the activation of the downstream PI3K/AKT pathway." (PMID 31864394, 2019). "TSLP released from human cervical carcinoma cells promoted angiogenesis and cancer growth, while the blockage of TSLP suppressed tumor growth and infiltration." (PMID 31023965, 2019). "Cervical carcinoma HeLa and CaSki cells released TSLP in vitro." (PMID 40873585, 2025). "Moreover, cervical cancer cell-derived TSLP increased the secretion of VEGFA and IL-8 by eosinophils, thus promoting angiogenesis in HUVEC cells." (PMID 40050933, 2025). "Additionally, overexpression of TSLP enhances the interaction between eosinophils and cervical cancer cells to promote angiogenesis in human umbilical vein endothelial cells (HUVECs)." (PMID 37083272, 2023). "Besides, the interaction between cervical cancer cell-derived TSLP and eosinophils regulates IL-18 and VEGF production, resulting in stimulation of the angiogenesis of human umbilical vein epithelial cells." (PMID 33652749, 2021). "Several studies reported a pro-tumor role for TSLP in cervical cancer." (PMID 33042121, 2020). "In contrast, in HeLa and SiHa cervical cancer cells chronic hypoxia increases the expression of this chemokine, although in an indirect manner—via increased expression of thymic stromal lymphopoietin (TSLP), which in turn depends directly on HIF-1." (PMID 32781743, 2020).
cervical carcinoma (continued). "But, in the middle and the late stage, the level of the TSLP expression was correlated with tumor growth and metastasis, and tumor-derived TSLP could act on TSLPR+ endothelial cells to promote angiogenesis in cervical cancer." (PMID 32351590, 2020). "TSLP has an important role in promoting the growth of vascular endothelial cells and angiogenesis, which could further promote the development and progression of cervical cancer." (PMID 31885639, 2019). "Moreover, TSLP produced by cervical cancer cells may promote angiogenesis, and down-regulate miR-132 expression, favoring tumor development." (PMID 30214685, 2018). "Tumor-derived thymic stromal lymphopoietin (TSLP) can activate eosinophil to increase the expression of IL-4, IL-5, IL-10 and IL-13, and promote the proliferation of cervical cancer cells." (PMID 36874093, 2023). "Mechanistic studies reveal that thymic stromal lymphopoietin (TSLP) activates eosinophils that promote proliferation and survival of cervical cancer cells through upregulating Ki-67, proliferating cell nuclear antigen (PCNA) and BCL-2 and downregulating Fas and Fas ligand (FasL)." (PMID 34359674, 2021).
chronic obstructive pulmonary disease (22 papers, 2015 to 2025). A chronic and progressive lung disorder characterized by the loss of elasticity of the bronchial tree and the air sacs, destruction of the air sacs wall, thickening of the bronchial wall, and mucous accumulation in the bronchial tree. "Aberrant TSLP, IL-4, and IL-13 levels and activities in the airway lead to the onset and sustaining of atopic asthma and chronic obstructive pulmonary disease (COPD)." (PMID 41294800, 2025). "Tezepelumab, a monoclonal antibody targeting TSLP, received approval in 2021 for the treatment of asthma, chronic obstructive pulmonary disease (COPD), and CRSwNP." (PMID 37138733, 2023). "The prevalence of TSLP in other respiratory diseases, such as chronic obstructive pulmonary disease, also suggests that TSLP may be involved in other T2-independent inflammatory pathways." (PMID 35572064, 2022). "TSLP is also involved in chronic inflammatory diseases such as chronic obstructive pulmonary disease (COPD) and inflammatory bowel disease (IBD)." (PMID 39726595, 2024). "It is reported that a chromatin remodelling associated with IL-17A-mediated IKKα activity and histone H3 acetylation in Lys14 increase the TSLP mRNA transcription in bronchial epithelial cells during chronic obstructive pulmonary disease (COPD) pathogenesis." (PMID 33652749, 2021). "The aim of our study was to determine periostin and TSLP concentration in serum and induced sputum (IS) in patients with atopic asthma, chronic obstructive pulmonary disease (COPD), and controls, as well as to evaluate the potential link between periostin, TSLP, and Th2 immune response." (PMID 33203095, 2020).
COVID-19 (20 papers, 2020 to 2025). A disease caused by infection with severe acute respiratory syndrome coronavirus 2. "Increased TSLP levels are found in COVID-19 patients and have been associated with the severity of this disease." (PMID 38273281, 2024). "We explored the potential associations between genetic polymorphisms in IL-33 and TSLP and COVID-19 outcomes." (PMID 37761861, 2023). "In this study, we investigated the production of TSLP during SARS-CoV-2 infection in hospitalized COVID-19 patients and its association with other factors including duration of hospital stay." (PMID 36851770, 2023). "IL-33, TSLP, and IL-25 have been implicated as potential predictors of severe COVID-19 outcomes, associated with severe lung inflammation, making them promising candidates for disease severity control." (PMID 37761861, 2023). "Moreover, a minor allele within the IL-33 gene (rs3939286) was found to be associated with a protective effect against severe COVID-19 (p < 0.05), and minor alleles of the TSLP gene (rs2289276 and rs13806933) were found to significantly reduce TSLP protein levels in serum (p < 0.05)." (PMID 37761861, 2023). "None of the other measured mediators related to eosinophils and the T2 response (CCL26, IL-3, IL-4, IL-5, CD44, TSLP, or GM-CSF) displayed any significant differences between the different timepoints and between COVID-19 versus controls." (PMID 40710346, 2025). "Recent studies have shown that TSLP levels correlate with the duration of hospitalization in COVID-19 patients." (PMID 40475767, 2025). "Based on this finding, the use of TSLP inhibitors has been suggested to control severe lung inflammation in COVID-19." (PMID 38273281, 2024). "Nevertheless, previous research has reported a correlation between TSLP levels and the duration of hospitalization in COVID-19 patients, suggesting a possible role of TSLP in disease progression." (PMID 37761861, 2023). "Increased TSLP levels were detected in the plasma of hospitalized COVID-19 patients (603.4 ± 75.4 vs 997.6 ± 241.4 fg/mL, mean ± SEM), the levels of which correlated with duration of stay in hospital (β: 0.11; 95% confidence interval (CI): 0.01–0.21)." (PMID 36851770, 2023). "We conducted a multinomial regression analysis to explore potential relationships between TSLP and IL-33 SNPs and COVID-19 severity." (PMID 37761861, 2023). "This study provides novel insights into the role of alarmin cytokines, specifically IL-33, IL-25, and TSLP, in COVID-19." (PMID 37761861, 2023). "While some studies suggest that little to no TSLP is detectable in epithelial cell supernatants or the plasma of infected patients during SARS-CoV-2 infection, others showed an elevation of TSLP in the circulatory system of COVID-19 patients." (PMID 36851770, 2023). "In support of this suggestion, a recent report suggested that alarmin cytokines such as TSLP are targets of major therapeutic interest in COVID-19, although few clinical trials are being conducted at present to target these during COVID-19 infection." (PMID 36851770, 2023). "To test the possibility that SARS-CoV-2 infection leads to TSLP accumulation in the bloodstream, we measured the levels of serum TSLP in individuals affected by COVID-19 at two time points, namely at hospital admission and 7 days post admission." (PMID 33536486, 2021). "Serum IL-26, a cytokine involved in IL-17 pathway, TSLP and adiponectin were measured and correlated to lipid COVID-19 patient profiles." (PMID 33536486, 2021). "However, they also identified alarmins, such as IL-25, IL-33, and TSLP, which they suggested were likely to contribute to lung inflammation during different phases of disease progression in COVID-19." (PMID 37631998, 2023). "Considered together, these findings suggest that the deleterious effects of epithelial-secreted TSLP in COVID-19 may occur downstream of the epithelium." (PMID 37631998, 2023).
COVID-19 (continued). "The concentration of alarmin cytokines IL-33, TSLP, and IL-25 were compared in COVID-19-positive and -negative patients, and the association of alarmin cytokine levels with disease severity and age-related variations was evaluated." (PMID 37761861, 2023). "We observed that plasma TSLP levels increased from 603.4 ± 75.4 fg/mL in healthy participants (values for plasma samples shown as mean ± SEM) to 997.6 ± 241.4 fg/mL in hospitalized COVID-19 patients." (PMID 36851770, 2023). "Our analysis also suggests, for the first time, that plasma levels of TSLP at the time of hospitalization could plausibly indicate the period of hospitalization in COVID-19 patients." (PMID 36851770, 2023). "Based on our findings, TSLP may be considered an important therapeutic target for COVID-19 treatment." (PMID 36851770, 2023). "A major strength of this study is that our findings demonstrate for the first time that plasma TSLP may be a determinant of the period of hospitalization in COVID-19 patients." (PMID 36851770, 2023). "IL-9 and TSLP could be other targets to inhibit Th2 responses in COVID-19 patients, as these molecules promote allergic inflammation (Temann and others 2002; Ito and others 2012; Koch and others 2017)." (PMID 35674675, 2022). "While IL-17c and TSLP levels predicted need for intensive care in COVID-19 subjects." (PMID 36116160, 2022). "TSLP was significantly lower in both moderate and severe COVID-19 compared with ARDS and sepsis." (PMID 32706339, 2020). "The targeted inhibition of TSLP could help prevent the damaging sequelae of COVID-19." (PMID 36851770, 2023). "Overall, our findings suggest that alarmin cytokines (IL-33, TSLP, and IL-25) could serve as potential therapeutic targets to modulate disease severity in COVID-19, and genetic variations influencing protein production can also protect against developing severe COVID-19." (PMID 37761861, 2023). "TSLP and its isoforms may contribute to the Kawasaki Syndrome seen in SARS-CoV-2 infected children, or to increased thrombosis in COVID-19 severe cases, through activation of vascular endothelial cells and/or platelet activation via TSLP-dependent PI3K/Akt signaling 57-59." (PMID 36313221, 2022). "We previously demonstrated that levels of multiple cytokines, including TH2 cytokines such as interleukin (IL)-4, macrophage-derived chemokine (MDC) and thymic stromal lymphopoietin (TSLP), remained elevated for an extended period of time following SARS-CoV-2 infection." (PMID 36101871, 2022). "Indeed, high TSLP levels coincide with a Th2 cytokine profile in our COVID-19 cohort." (PMID 33995342, 2021). "In contrast, the expression levels of tumor necrosis factor-related weak inducer of apoptosis (TWEAK), thymic stromal lymphopoietin (TSLP), and matrix metalloproteinases 1 and 3 (MMP-1 and MMP-3) were specifically upregulated in COVID-19." (PMID 40598558, 2025). "Plasma TSLP in COVID-19 patients significantly correlated with duration of hospitalization, while SARS-CoV-2 induced TSLP secretion from bronchial epithelial cells in vitro." (PMID 36851770, 2023). "Our findings indicate that plasma levels of TSLP, IL-15, and CXCL10/IP-10 were elevated in COVID-19 patients over that of normal uninfected controls." (PMID 36851770, 2023). "TSLP levels were not significantly different, though numerically higher in the COVID-19-positive group (p = 0.635)." (PMID 37761861, 2023). "Although there was a 65% increase in TSLP in the COVID-19 group than the healthy participants, this difference did not achieve the threshold for statistical significance in multivariable analysis (p = 0.25)." (PMID 36851770, 2023). "Our objective in this study was to determine whether TSLP levels increase in COVID-19 patients and if SARS-CoV-2 induces TSLP expression in bronchial epithelial cells." (PMID 36851770, 2023). "Conversely, TWEAK, TSLP, MMP-1, and MMP-3 are upregulated only in COVID-19." (PMID 35674675, 2022).
COVID-19 (continued). "Another immune signature detected in critically ill patients with COVID-19 includes the type 2 cytokines IL-4, IL-5, IL-13, and TSLP, related to noninfectious lung diseases (Choreño-Parra and others 2021)." (PMID 35647937, 2022). "Meanwhile, COVID-19 displayed an immune profile distinguished by increased Th1 (IL-12, IFN-γ) and Th2 (IL-4, IL-5, IL-10, IL-13) cytokine levels, along with IL-1β, IL-6, CCL11, VEGF, TWEAK, TSLP, MMP-1, and MMP-3." (PMID 33995342, 2021). "TWEAK, TSLP, MMP-1, and MMP-3 were elevated in COVID-19 cases." (PMID 33995342, 2021). "Alternatively, identifying upstream regulators of the inflammatory pathway, as for example IL-17 studied in mice 48, or regulators of lymphopoiesis, as for example IL-7 and thymic stromal lymphopoietin (TSLP), may be needed to understand COVID-19 cytokine pathogenesis." (PMID 36313221, 2022). "Additionally, although the immunity benefits of IFN-III have been revealed, it is not yet clear whether the IFN-III/TSLP axis functions in defeating severe acute respiratory syndrome coronavirus 2 (SARS-CoV-2) in the context of coronavirus disease 2019 (COVID-19) pandemic." (PMID 37809098, 2023). "Previous studies show conflicting observations in blood TSLP in COVID-19, while none report SARS-CoV-2 inducing TSLP expression in bronchial epithelial cells." (PMID 36851770, 2023). "Finally, TSLP could be another target to inhibit Th2 responses in COVID-19 patients, as this molecule promotes allergic inflammation, and indeed, high levels of TSLP were observed in our cohort of COVID-19 but not pandemic influenza A(H1N1) subjects." (PMID 33995342, 2021).